NOVA2 (NOVA alternative splicing regulator 2)
Description:
Functions to regulate alternative splicing in neurons by binding pre-mRNA in a sequence-specific manner to activate exon inclusion or exclusion. It binds specifically to the sequences 5'-YCAY-3' and regulates splicing in only a subset of regulated exons. Binding to an exonic 5'-YCAY-3' cluster changes the protein complexes assembled on pre-mRNA, blocking U1 snRNP binding and exon inclusion, whereas binding to an intronic 5'-YCAY-3' cluster enhances spliceosome assembly and exon inclusion. With NOVA1, they perform unique biological functions in different brain areas and cell types. Uniquely regulates alternative splicing events of a series of axon guidance related genes during cortical development, being essential for central nervous system development by regulating neural networks wiring. Regulates differentially alternative splicing on the same transcripts expressed in different neurons. This includes functional differences in transcripts expressed in cortical and cerebellar excitatory versus inhibitory neurons where is required for, respectively, development of laminar structure and motor coordination and synapse formation. Also the regulation the regulation of intron retention can sequester the trans-acting splicing factor PTBP2, acting as a variable cis-acting scaffolding platform for PTBP2 across various natural conditions (By similarity).
Synonyms: ANOVA; NOVA3; NOVA-2; NEDASB
Tractability: PROTAC: UniProt records ubiquitination sites on it; its protein half-life has been measured.
Gene: Protein-coding gene on chromosome 19 (45,933,734 to 45,974,044, reverse strand). Ensembl gene ENSG00000104967.
Subcellular location: Nucleus
Subcellular location (Human Protein Atlas): Golgi apparatus; Nuclear bodies; Nucleoplasm
Gene Ontology:
Molecular function: RNA binding; sequence-specific mRNA binding; mRNA binding; nucleic acid binding
Biological process: neuron differentiation; regulation of alternative mRNA splicing, via spliceosome; regulation of RNA metabolic process; central nervous system neuron development; mRNA splicing, via spliceosome; negative regulation of cold-induced thermogenesis; regulation of axon guidance
Cellular component: nucleus
Genetic constraint (gnomAD): Loss-of-function variants: 5 observed, 17.21 expected, observed/expected ratio (o/e) 0.29, 90% interval 0.15 to 0.61. The upper end of that interval is the gene's LOEUF score, 0.61, which puts it in group 2 of 6, group 1 being the genes least tolerant of losing a copy. Missense variants: 339 observed, 493.06 expected, observed/expected ratio (o/e) 0.69, 90% interval 0.63 to 0.75. Synonymous variants: 288 observed, 252.63 expected, observed/expected ratio (o/e) 1.14, 90% interval 1.03 to 1.26.
Gene-disease validity (ClinGen):
ClinGen rates the evidence that NOVA2 causes each of these diseases.
complex neurodevelopmental disorder (autosomal dominant): Definitive. A disorder that involves more than one phenotype associated with the central nervous system, including but not limited to intellectual disability, autism, and seizures (epilepsy).
Homologues: Orthologues: chimpanzee NOVA2 (100% identical), dog NOVA2 (100% identical), macaque NOVA2 (99% identical), pig NOVA2 (99% identical), mouse Nova2 (99% identical), rat Nova2 (96% identical), rabbit NOVA2 (95% identical), tropical clawed frog nova2 (62% identical), Caenorhabditis elegans fubl-3 (14% identical), Caenorhabditis elegans fubl-4 (14% identical). Paralogues in human: NOVA1 (74% identical), FUBP1 (23% identical), KHSRP (21% identical), FUBP3 (20% identical), PCBP3 (20% identical), PCBP2 (18% identical), PCBP4 (17% identical), HNRNPK (17% identical), IGF2BP2 (17% identical), PCBP1 (17% identical), IGF2BP1 (16% identical), IGF2BP3 (15% identical).
Diseases named in the same sentence as NOVA2 in open-access papers:
NOVA2 is named in the same sentence as 19 diseases in open-access papers, as found by Europe PMC text mining. Sharing a sentence is not in itself a finding about the gene and the disease. The quoted sentences say what the papers report.
ovarian carcinoma (4 papers, 2019 to 2023). A malignant neoplasm originating from the surface ovarian epithelium. "NOVA2 was also found to be upregulated specifically in ECs in several cancers such as colorectal and ovarian cancer." (PMID 35927413, 2023). "Notably, Nova2 was recently reported to be upregulated in the vasculature of colorectal and ovarian cancers, and high Nova2 expression correlates with shorter overall survival of ovarian cancer patients." (PMID 31771184, 2019). "The importance of Nova2 in angiogenesis is also emphasized by recent data showing that it is upregulated in cancer vasculature, including ovarian cancer (OC) and colorectal carcinoma, while no Nova2 expression is detectable in other cell types present in the tumors." (PMID 31771184, 2019).
colorectal carcinoma (3 papers, 2019 to 2020). A malignant epithelial neoplasm that arises from the colon or rectum and invades through the muscularis mucosa into the submucosa. "Finally, we found that Netrin-1/Deleted in Colorectal Cancer (Dcc) proteins acted downstream of Nova2 to suppresses neuronal migration." (PMID 32271715, 2020).
lung carcinoma (3 papers, 2021 to 2023). "NOVA2, a key AS regulator of vascular morphogenesis, was overexpressed in lung carcinoma but its expression was negatively correlated with the prognosis of PTC patients in our analysis." (PMID 34722250, 2021). "A study by Haiping Xiao reported that miR-7-5p regulates target neuro-oncological ventral antigen 2 (NOVA2) expression to suppress tumor metastasis of non-small cell lung cancer (NSCLC), and when NOVA2 was overexpressed, the miR-7-5p-mediated inhibitory effect on lung cancer cells was reversed." (PMID 34713767, 2021).
epilepsy (2 papers, 2016 to 2023). A brain disorder characterized by episodes of abnormally increased neuronal discharge resulting in transient episodes of sensory or motor neurological dysfunction, or psychic dysfunction. "There was no apparent phenotype in Nova2 heterozygotes, although we previously found that when assessed by electroencephalography, 6 month old Nova2+/- (and Nova1+/-) mice had frequent synchronous cortical interictal discharges consistent with epilepsy." (PMID 27223325, 2016).
gastric cancer (2 papers, 2023 to 2025). A primary or metastatic malignant neoplasm involving the stomach. "For instance, transglutaminase-2 (TGM2) and neuro oncological ventral antigen 2 (NOVA2) have been implicated in poor prognosis for gastric cancer patients." (PMID 40248695, 2025). "In addition, we report that NOVA2 is also upregulated in ECs of gastric cancer (GC), and its expression correlates with poor overall survival of GC patients." (PMID 37175811, 2023).
glioma (2 papers, 2019 to 2021). A benign or malignant brain and spinal cord tumor that arises from glial cells (astrocytes, oligodendrocytes, ependymal cells). "In a human glioma malignancy study the circRNA U2 auxiliary factor 35 kDa subunit (circ-U2AF1) was found upregulated along with neuro-oncological ventral antigen 2 (NOVA2)." (PMID 31080413, 2019).
neuroblastoma (2 papers, 2011 to 2015). Neuroblastoma (NB) is the most common solid, extracranial childhood tumor. "As Nova2 has previously been implicated in the exclusion of exons 9B and 9C in Dab1, we examined the expression of this splicing factor in neuroblastoma and retinoblastoma cell lines." (PMID 22163036, 2011). "Nova2 was only detected in neuroblastoma cells, suggesting a correlation between Nova2 expression and increased levels of Dab1-E-like splice forms in neuroblastoma." (PMID 22163036, 2011).
Cerebellar atrophy (1 paper, 2022). Cerebellar atrophy is defined as a cerebellum with initially normal structures, in a posterior fossa with normal size, which displays enlarged fissures (interfolial spaces) in comparison to the foliae secondary to loss of tissue. "Furthermore, while the progressive motor discoordination observed in the conditional mouse model with specifical Nova2 inactivation is recapitulated in NOVA2 patients, there is no comparable cerebellar atrophy." (PMID 35607920, 2022).
hepatocellular carcinoma (1 paper, 2025). A malignant tumor that arises from hepatocytes. "Exosomal circRNA-100,338 regulates angiogenesis by interacting with the RNA-binding protein neuro-oncological ventral antigen 2 (NOVA2), activating the mTOR pathway, thereby promoting hepatocellular carcinoma metastasis." (PMID 40002766, 2025).
non-small cell lung carcinoma (1 paper, 2021). A group of at least three distinct histological types of lung cancer, including non-small cell squamous cell carcinoma, adenocarcinoma, and large cell carcinoma. "In contrast, in non-small cell lung cancer, miR-7 inhibits growth and metastasis via the NOVA alternative splicing regulator 2 (NOVA2) and Bcl-2, a critical regulator of apoptosis." (PMID 33673265, 2021).
tumor (8 papers, 2019 to 2024). "Recently, NOVA2 has been reported significantly upregulated in tumor ECs of several cancer types, including ovarian, colorectal, hepatocellular, and head-neck squamous cell cancers." (PMID 37175811, 2023). "Collectively, our data are in line with the possibility that the NOVA2/RapGEF6 circuit in tumor ECs contributes to the phenotypical and functional vascular aberrancies observed in GC patients." (PMID 37175811, 2023). "NOVA2 is upregulated in tumor endothelial cells (ECs) of different cancers, thus representing a potential driver of tumor blood vessel aberrancies." (PMID 37175811, 2023). "First, downregulation was observed for NOVA Alternative Splicing Regulator 2 (NOVA2), which is an alternative splicing factor, proposed to also be involved in tumor progression." (PMID 36680249, 2023). "In particular, Dll4 represents a potential biomarker and therapeutic target in OC, a type of tumor characterized by strong angiogenesis and showing Nova2 upregulation selectively in the tumor vasculature." (PMID 31771184, 2019). "Further study showed that miR-7-5p suppresses tumor metastasis of NSCLC by targeting neuro-oncological ventral antigen 2 (NOVA2)." (PMID 31832068, 2019). "NOVA2 has been proposed to be a positive regulator of β-catenin, which, in turn, promotes the expression of a variety of oncogenes, therefore promoting transformation and tumor progression." (PMID 36680249, 2023). "Collectively, our results strongly support a role for NOVA2 in controlling the dependence receptor function of UNC5B in ECs and suggest that the NOVA2/UNC5B axis may represents a post-transcriptional pathway relevant to both developmental and tumor angiogenesis." (PMID 34381052, 2021).
cancer (7 papers, 2019 to 2023). A tumor composed of atypical neoplastic, often pleomorphic cells that invade other tissues. "Interestingly, previous work suggests a role for NOVA2, which is upregulated in a variety of cancer cell types, in Wnt signaling." (PMID 36680249, 2023). "NOVA2, a member of the Nova family of neuron-specific RBPs, was also upregulated in the quasi-mesenchymal cells from both cell lines, possibly as the result of the differential expression of miR-7-5p, as previously shown in non-small cell lung and prostate cancer." (PMID 36346211, 2022). "The immunohistochemistry (IHC) results showed that KHSRP, SRSF3 and RBM9 were located in nucleus, and the expression of SRSF3 and RBM9 were significantly lower in cancer than normal thyroid, while there was no significantly different between KHSRP, NOVA2 and PTBP2 in carcinoma and normal tissues." (PMID 34722250, 2021).
neurodegenerative disease (1 paper, 2020). A disorder of the central nervous system characterized by gradual and progressive loss of neural tissue and neurologic function. "Neuro-oncological ventral antigen 2 (Nova2), a neuronal-specific RNA binding protein, was first identified as an autoimmune antigens in the neurodegenerative disease POMA (paraneoplastic opsoclonus myoclonus ataxia)." (PMID 32271715, 2020).
NOVA2 also shares sentences with these, for which no sentence is quoted: Angelman syndrome (1 paper); bipolar disorder (1); cardiomyopathies (1); Laryngospasm (1); neurological diseases (1); retinoblastoma (1).